LCP2 (lymphocyte cytosolic protein 2)
Description:
Adapter protein primarily involved in signaling pathways within T-cells, as well as other immune cells such as platelets, mast cells, and natural killer (NK) cells. Plays a crucial role for transducing signal from the T-cell receptor (TCR) after antigen recognition leading to T-cell activation. Mechanistically, once phosphorylated by the kinase ZAP70, mediates interactions with the guanine-nucleotide exchange factor VAV1, the adapter protein NCK and the kinase ITK. In turn, stimulates the activation of PKC-theta/PRKCQ and NF-kappa-B transcriptional activity in response to CD3 and CD28 costimulation. Also plays an essential role in AGER-induced signaling pathways including p38 MAPK and ERK1/2 activation leading to cytokine release and pro-inflammatory responses.
Synonyms: SLP76; SLP-76; IMD81
Tractability: PROTAC: ubiquitination databases record sites on it; its protein half-life has been measured.
Gene: Protein-coding gene on chromosome 5 (170,246,233 to 170,297,820, reverse strand). Ensembl gene ENSG00000043462.
Subcellular location: Cytoplasm
Subcellular location (Human Protein Atlas): Cytosol
Pathways (Reactome):
Immune System: DAP12 signaling; FCERI mediated Ca+2 mobilization; FCERI mediated MAPK activation; Generation of second messenger molecules
Hemostasis: GPVI-mediated activation cascade
Gene Ontology:
Molecular function: protein binding; protein-macromolecule adaptor activity
Biological process: positive regulation of protein kinase activity; T cell receptor signaling pathway; cell surface receptor protein tyrosine kinase signaling pathway; immune response; intracellular signal transduction; mast cell activation; immune system process
Cellular component: cytosol; plasma membrane raft; TCR signalosome; cytoplasm; cell-cell junction
Genetic constraint (gnomAD): Loss-of-function variants: 16 observed, 52.22 expected, observed/expected ratio (o/e) 0.31, 90% interval 0.21 to 0.47. The upper end of that interval is the gene's LOEUF score, 0.47, which puts it in group 2 of 6, group 1 being the genes least tolerant of losing a copy. Missense variants: 405 observed, 463.35 expected, observed/expected ratio (o/e) 0.87, 90% interval 0.81 to 0.95. Synonymous variants: 159 observed, 169.62 expected, observed/expected ratio (o/e) 0.94, 90% interval 0.82 to 1.07.
Gene-disease validity (ClinGen):
ClinGen rates the evidence that LCP2 causes each of these diseases.
immunodeficiency 81 (autosomal recessive): Definitive. A human immunodeficiency characterized by early-onset life-threatening infections, combined T and B cell immunodeficiency, severe neutrophil defects, and impaired platelet aggregation, caused by a variation in the SLP76 gene.
Homologues: Orthologues: chimpanzee LCP2 (99% identical), macaque LCP2 (98% identical), rabbit LCP2 (92% identical), dog LCP2 (90% identical), pig LCP2 (90% identical), guinea pig LCP2 (87% identical), rat Lcp2 (83% identical), mouse Lcp2 (82% identical), tropical clawed frog lcp2 (44% identical), zebrafish lcp2a (35% identical), zebrafish lcp2b (28% identical). Paralogues in human: CLNK (22% identical), BLNK (20% identical), SH2D6 (14% identical).